EPHX2 (epoxide hydrolase 2)
Diseases named in the same sentence as EPHX2 in open-access papers (continued):
Sharing a sentence is not in itself a finding about the gene and the disease.
Stroke (29 papers, 2010 to 2025). Sudden impairment of blood flow to a part of the brain due to occlusion or rupture of an artery to the brain. "In line with this, sEH gene polymorphisms in the human sEH gene (EPHX2) have been shown to alter stroke incidence and ischemic outcome." (PMID 25642188, 2014). "In humans, sEH gene (EPHX2) polymorphisms have been shown to alter stroke incidence and ischemic outcome." (PMID 25642188, 2014). "Genetic variations in EPHX2 have been linked to the occurrence of stroke in rats and humans." (PMID 40129060, 2025). "We recently demonstrated a genetic effect of sEH encoded by the EPHX2 gene on the progression of IgA nephropathy and on renal allograft survival, and some studies have shown a protective effect of sEH inhibitors against IRI in stroke and ischemia-induced myocardial damage." (PMID 22590647, 2012).
atherosclerosis (27 papers, 2008 to 2025). A disease characterized by the build-up of fatty material and calcium deposition in the arterial wall resulting in partial or complete occlusion of the arterial lumen. "It was demonstrated that endothelial Nox4 protects against atherosclerosis, and the underlying mechanism involves the inhibition of soluble epoxide hydrolase 2 (sEH, gene EPHX2), a pro-inflammatory and atherogenic factor." (PMID 39598345, 2024). "The Atherosclerosis Risk in Communities (ARIC) study reports that the K55R variant of Ephx2, which results in elevated sEH activity, increases the risk of congenital heart disease." (PMID 34689162, 2021). "Polymorphisms in EPHX2 gene have been linked to the pathogenesis of coronary heart disease (CHD) and atherosclerosis; therefore, EPHX2 has been implicated as a potential cardiovascular disease-susceptibility gene." (PMID 19452041, 2008). "In vitro and in vivo studies suggest that EPHX2 might be implicated in the pathogenesis and development of OS, endothelial dysfunction, and atherosclerosis." (PMID 34040693, 2021). "The EPHX2 gene which encodes soluble EPHX2 might be implicated in the pathogenesis and development of OS and atherosclerosis." (PMID 34040693, 2021). "Since obesity is a major risk factor for CHD and atherosclerosis, down-regulation of EPHX2 by HCA-SX in human adipocytes may exert protective effect against these cardiovascular diseases." (PMID 19452041, 2008). "Moreover, epidemiologic data have repeatedly reported that genetic variations of the EPHX2 gene are associated with the onset of CV disease in several populations, and thus, EPHX2 might be a potential atherosclerosis-susceptibility gene." (PMID 34040693, 2021). "Although several studies have examined the association between various polymorphisms of the EPHX2 gene and CV outcomes, there are no data regarding the role of rs2741335 and rs11780592 EPHX2 polymorphisms in atherosclerosis and endothelial dysfunction." (PMID 34040693, 2021). "Thus, in agreement with our study, there is a growing body of evidence suggesting a central role for EPHX2 in the regulation of endothelial function and the pathogenesis of atherosclerosis." (PMID 34040693, 2021). "By catalyzing this reaction, soluble EPHX2 promotes inflammation, OS, and atherosclerosis." (PMID 34040693, 2021). "Furthermore, the effect of pharmacological inhibition of sEH in human blood vessels as well as the association between EPHX2 sequence variants and risk of subclinical atherosclerosis has been published." (PMID 19814804, 2009). "This review synthesizes current evidence on the interplay between inflammation, oxidative stress, and atherosclerosis in CKD, with a special focus on emerging molecular biomarkers—PCSK9, EPHX2, AOPPs, and TBARSs—and their integration with clinical indices." (PMID 40868936, 2025).
Alzheimer disease (26 papers, 2019 to 2026). A progressive, neurodegenerative disease characterized by loss of function and death of nerve cells in several areas of the brain leading to loss of cognitive function such as memory and language. "Genetic and human brain proteomic data have linked EPHX2, the gene encoding sEH, to Alzheimer’s disease, especially the rs7341557 variant, which is now considered an Alzheimer’s disease genetic risk factor." (PMID 41007636, 2025). "EPHX2 encodes soluble epoxide hydrolase (sEH), the overexpression of which has been implicated in Scz and other diseases with a neuroinflammatory component (e.g., Alzheimer’s Disease)." (PMID 38906991, 2024). "We found two lifespan candidate loci which were previously associated with Alzheimer’s disease: the newly identified EPHX2/CLU and, perhaps the most widely reported candidate lifespan locus: APOE." (PMID 31484785, 2019). "In addition, high EPHX2 levels in the blood or brain are linked to hippocampal volume and Alzheimer’s disease progression in humans." (PMID 41007636, 2025). "The expression of EPHX2 was also found to be modified by other Alzheimer’s disease-related factors, such as the activity of the rs2279590 variant of the clusterin (CLU) gene, as well as obesity, a recognized risk factor for dementia." (PMID 41007636, 2025). "Another study exploring the impact of EPHX2 deletion in a murine model of Alzheimer’s disease revealed lower levels of Aβ deposition in the hippocampus and motor cortex of these mice." (PMID 41007636, 2025). "Previous studies have found that the deletion of Ephx2 and sEH inhibitor could ameliorate cognitive declines in Alzheimer's disease (AD) mouse models." (PMID 40259894, 2025). "Similarly, EPHX2 gene deletion in Alzheimer’s disease mouse models resulted in reduced tau pathology, further supporting the potential role of sEH in Alzheimer’s disease pathology." (PMID 41007636, 2025). "Interestingly, the EPHX2 gene was also recently identified by Mendelian randomization as a therapeutic target for Alzheimer disease." (PMID 39125098, 2024). "In concurrence with this, studies have shown EPHX2 to be a targetable gene for Alzheimer’s disease management, without potential side effects." (PMID 41007636, 2025).
cardiac hypertrophy (25 papers, 2012 to 2025). "The further detected candidate gene Ephx2 was previously reported as a promising candidate for cardiac hypertrophy in rodents and patients." (PMID 25646840, 2015). "Because the level of 4 HETEs increased in EPHX2−/− mice was found associated with vascular remolding by a pro-inflammatory effect, we next explored the different physiological effects of EPHX2 gene deletion and inhibition in a mouse cardiac hypertrophy model." (PMID 24718617, 2014). "Both EPHX2 gene deletion and inhibition protected against AngII-induced cardiac hypertrophy." (PMID 24718617, 2014). "In Ephx2 (−/−) mouse experiments, sEH deletion reduced bFGF expression in cardiac tissues by inhibiting MAPK activation, thereby alleviating mouse cardiac hypertrophy." (PMID 38628644, 2024).
depression (24 papers, 2017 to 2025). "We also found a significant association between a specific SNP of gene EPHX2 and depression, as well as SNPs of EPHX2, OXTR, NRG1 with stress symptoms." (PMID 31801286, 2019). "The SNP of EPHX2 (rs17466684) gene polymorphism is associated with depression symptoms among Malaysian women with GDM." (PMID 31801286, 2019). "Single nucleotide polymorphisms (SNPs) recorded a significant association between SNP of EPHX2 (rs17466684) and depression symptoms (AOR = 7.854, 95% CI = 1.330–46.360) and stress symptoms (AOR = 7.664, 95% CI = 1.579–37.197)." (PMID 31801286, 2019). "Polymorphism in EPHX2 contributes to the odds of suffering from depression, anxiety, and stress symptoms in the Japanese and Malaysian population." (PMID 31801286, 2019). "Finally, epoxide hydrolase 2 (EPHX2) emerged as a candidate for ANR associated with increased depression and anxiety in a high-throughput sequencing study." (PMID 28093506, 2017). "Though we did not found a direct effect between the mRNA expression level of EPHX2 and MDD, a significant indirect effect was found through cognitive function between depression and the rs9331949 of EPHX2." (PMID 40259894, 2025). "Recent studies have indicated the critical roles for EPHX2/P2X2 in the pathophysiology of depression." (PMID 40226652, 2024). "However, a previous study found that oral administration of F. rodentium in antibiotic-treated resilient Ephx2 KO mice led to depression-like behaviors." (PMID 36033889, 2022). "Based on logistic regression in this study, we reported that there is significant between SNP (rs17466684) of Epoxide Hydrolase 2 gene (EPHX2) with depression symptoms (AOR = 7.854, 95% CI = 1.330–46.360) and stress symptoms (AOR = 7.664, 95% CI = 1.579–37.197)." (PMID 31801286, 2019). "SNPs in EPHX2 (rs17466684), OXTR (rs53576) and NRG1 (rs2919375) are also associated with stress symptoms adjusted for ethnicity, religion, marital status, treatment regimens, past obstetric history of GDM, underlying with allergy and asthma and a family history of depression and anxiety." (PMID 31801286, 2019). "These custom SNPs provide excellent coverage of many previously suggested and functionally important candidate genes for depression, anxiety and stress, including NPY5R; ANO2; EPHX2; TPH2; NRG1; LHPP; FKBP5; SDK2; RORA; OXTR; BDNF; HTR2C; TEX51; and PLEKHG1." (PMID 31801286, 2019). "Although previous research has found a correlation between EPHX2 and P2X2 and the severity of depression, some features included in the model may contain similar information." (PMID 40226652, 2024). "Furthermore, the study confirmed that Ephx2 knockout (KO) mice do not exhibit depression-like behaviors even when exposed to chronic social defeat stress." (PMID 39599623, 2024).
endothelial dysfunction (21 papers, 2012 to 2025). In vascular diseases, endothelial dysfunction is a systemic pathological state of the endothelium (the inner lining of blood vessels) and can be broadly defined as an imbalance between vasodilating and vasoconstricting substances produced by (or acting on) the endothelium. "EPHX2 encodes soluble epoxide hydrolase, which degrades vasoprotective EETs, promoting vasoconstriction, oxidative stress, and endothelial dysfunction." (PMID 40868936, 2025). "Through degradation of EETs, EPHX2 promotes endothelial dysfunction, oxidative stress, and fibrosis—mechanisms central to CKD progression and its cardiovascular complications." (PMID 40868936, 2025). "Recent studies highlight the role of EPHX2 as a crucial mediator of endothelial dysfunction, glomerular injury, and progressive CKD." (PMID 40868936, 2025). "The EPHX2 enzyme, responsible for metabolizing epoxyeicosatrienoic acids (EETs), plays a pivotal role in endothelial dysfunction by attenuating vasodilatory and anti-inflammatory signaling pathways." (PMID 40868936, 2025). "Accordingly, the potentiation of CYP/epoxygenase activity compensates for endothelial dysfunction in females, while the estrogen-dependent downregulation of EPHX2 expression yields divergent effects in the circulation." (PMID 32192153, 2020). "Since EPHX2 regulates the cholesterol efflux and the oxidation of LDL in foam cells and macrophages, our study suggests that a genetic basis to endothelial dysfunction and OS might be present in diabetic CKD." (PMID 34040693, 2021). "Dysregulation among these nodes—characterized by reduced PLA2G2A and GGT5 expression together with elevated CYP2J2 and EPHX2—may reflect a disrupted AA-EET axis that favors oxidative stress, endothelial dysfunction, and maladaptive cardiac remodeling, ultimately contributing to HF progression." (PMID 41472876, 2025).
Insulin resistance (18 papers, 2012 to 2024). Increased resistance towards insulin, that is, diminished effectiveness of insulin in reducing blood glucose levels. "EPHX2 rs751141 (Arg287Gln) polymorphism has been reported to be associated with insulin resistance in patients with T2D in Japanese population." (PMID 37370090, 2023). "Moreover, polymorphism of Ephx2 has been shown to be a possible risk factor for developing insulin resistance and T2DM." (PMID 27496100, 2016). "Further studies are required to understand the crosstalk between EPHX2 levels and insulin resistance and the role of EPHX2 in adipose tissue, including its status in VAT." (PMID 32192153, 2020).
ischemic stroke (18 papers, 2013 to 2025). A stroke disorder caused by obstruction of blood flow to the brain, due to thrombotic (local blood clot formation) or embolic (due to a blood clot or other material traveling from another site) event. "The aim of this study was to investigate the relationship between the combined effect of MTHFR C677T (rs1801133) and EPHX2 G860A (rs751141) polymorphism and ischemic stroke in Chinese T2DM patients." (PMID 28409162, 2017). "The combined effect of MTHFR CC and EPHX2 GG genotypes also had a higher risk of ischemic stroke compared with the control group (OR = 2.73; P = .017)." (PMID 28409162, 2017). "Based on these observations, we performed genetic association analyses in a cohort of Chinese T2DM population from Beijing, China, aiming to evaluate the association of the combined effect of MTHFR C677T and EPHX2 G860A on ischemic stroke." (PMID 28409162, 2017). "When MTHFR polymorphism was CT genotype, the EPHX2 GG genotype group had a higher risk of ischemic stroke compared with the control group (OR = 3.12; P = .002), whereas EPHX2 GA + AA genotype group did not (OR = 1.84; P = .114)." (PMID 28409162, 2017). "In summary, our findings revealed that the combined effect of MTHFR C677T and EPHX2 G860A genotypes appears to be significantly associated with development of ischemic stroke in the Chinese T2DM group." (PMID 28409162, 2017). "The G860A polymorphism in the EPHX2 gene has been found to be associated with the risk of ischemic stroke, but results were inconsistent among different studies." (PMID 28409162, 2017). "Thus, an interesting result of our study is that the combined effect of the MTHFR TT and EPHX2 GG or GA + AA genotypes imparted a higher risk of ischemic stroke compared with the control group." (PMID 28409162, 2017). "Interactions between genetic and environmental factors play a substantial role in disease risk and Hcy level may influence the risk of ischemic stroke caused by EPHX2 polymorphism." (PMID 28409162, 2017). "Although EPHX2 gene knockout has a protective effect on experimental cerebral ischemia, it is still distant from clinical prevention and treatment of ischemic stroke." (PMID 36846137, 2023). "In animal models with ischemic stroke, administration of selective EPHX2 inhibitors was found to improve clinical outcomes, by suppressing OS and inflammation." (PMID 34040693, 2021). "Results of the risk of ischemic stroke with MTHFR C677T and EPHX2 G860A in these models were tabulated." (PMID 28409162, 2017). "The Ephx2 rs751141 and CYP2C8 rs17110453 polymorphisms may also act as a two-locus interaction which further increases the likelihood of ischemic stroke." (PMID 35682911, 2022). "To date, no study has investigated the association between EPHX2 G860A polymorphism and ischemic stroke in the Chinese T2DM population." (PMID 28409162, 2017). "Genetic distribution of EPHX2 G860A (GG, GA, and AA) trended toward statistical difference between T2DM participants with and without ischemic stroke (P = .053) and allele frequencies (A and G alleles) were significantly different (P = .023)." (PMID 28409162, 2017).
Parkinson disease (17 papers, 2017 to 2025). A progressive degenerative disorder of the central nervous system characterized by loss of dopamine producing neurons in the substantia nigra and the presence of Lewy bodies in the substantia nigra and locus coeruleus. "On the other hand, EPHX2 showed positive enrichment in oxidative phosphorylation and Parkinsons disease and negative enrichment in complement and coagulation cascades, hematopoietic cell lineage and cytokine cytokine receptor interaction." (PMID 41472876, 2025).
coronary heart disease (15 papers, 2008 to 2025). "Furthermore, enhanced sEH activity due to EPHX2 gene polymorphisms in humans was identified to be a potential risk factor for coronary heart disease." (PMID 35665247, 2022). "We investigated whether the EPHX2 K55R polymorphism, previously linked to significantly higher risk for coronary heart disease (CHD), was associated with the occurrence of restenosis after PCI." (PMID 19814804, 2009). "In conclusion, the present results suggest that the EPHX2 K55R polymorphism can be excluded as independent predictor for coronary heart disease or for the occurrence of restenosis in patients who had undergone primary successful PCI." (PMID 19814804, 2009).
diabetic nephropathy (15 papers, 2016 to 2026). "The aim of this study was to investigate the relationship between EPHX2 rs751141 (R287Q polymorphism) and diabetic nephropathy (DN) in Chinese type 2 diabetes (T2D)." (PMID 29629376, 2018). "Previous studies have shown that single nucleotide polymorphisms (SNPs) in CYP2J2, CYP2C8, CYP2C9, and EPHX2 are associated with diabetes and diabetic kidney disease (DKD); however, their genetic effects on GDM remain unclear." (PMID 37370090, 2023). "DNA methylation changes in the EPHX2 gene correlate with altered expression and disease severity in diabetic kidney disease, implicating epigenetic regulation of soluble epoxide hydrolase in renal inflammation and fibrosis." (PMID 40868936, 2025). "Finally, the involvement of EPHX2 in diabetic nephropathy was suggested in a case-control study in type 2 diabetic patients." (PMID 31213483, 2019). "A recent 2024 review highlights that early-phase clinical studies using EPHX2 inhibitors (such as GSK2256294) are underway in acute kidney injury and diabetic nephropathy, aimed at reversing oxidative injury and preserving tubular function." (PMID 40868936, 2025).
Hyperglycemia (15 papers, 2012 to 2025). An increased concentration of glucose in the blood. "In this study, Ephx2, Stc2, Cep19, Il15 and Fbxw7 genes were found to be associated with impaired glucose tolerance and hyperglycemia." (PMID 32095365, 2020). "We have previously shown that hyperglycemia, caused by beta cell destruction with STZ, increases EPHX2 expression in cerebral vessels and decreases EETs levels in brain." (PMID 24824753, 2014). "According to the mitigating effects of Ephx2 inactivation on renal injury induced by hyperglycaemia in mice, inhibition of its expression in the GK rat might underlie compensatory mechanisms to prevent renal dysfunction." (PMID 31213483, 2019).
heart failure (14 papers, 2015 to 2025). Inability of the heart to pump blood at an adequate rate to meet tissue metabolic requirements. "Transcripts of EPHX2, the gene that encodes sEH were significantly lower in ischemic human heart failure patients compared to controls." (PMID 36293289, 2022). "Elevated Ephx2 expression values were associated with heart failure in rats." (PMID 25646840, 2015). "Finally, the team showed that knockout of Ephx2 in mice provides protection from cardiac arrhythmias and improvement of heart failure-related clinical parameters compared to wild-type mice." (PMID 27736746, 2016). "Also in this study, eQTL analysis led to the initial identification of Ephx2 as a strong cis-regulated gene located within a heart failure QTL in the rat." (PMID 27736746, 2016). "Furthermore, Ephx2 was strongly correlated with ejection fraction (a clinical measure to characterize heart failure) and differentially expressed between the parental strains, an observation that was also validated at the protein level." (PMID 27736746, 2016). "However, in cardiac tissue of heart failure patients Ephx2 expression was found to be down-regulated." (PMID 25646840, 2015). "Furthermore, earlier studies identified Ephx2 as interesting drug target in heart failure." (PMID 25646840, 2015).